DYNC2LI1 (dynein cytoplasmic 2 light intermediate chain 1)
Description:
Acts as one of several non-catalytic accessory components of the cytoplasmic dynein 2 complex (dynein-2 complex), a motor protein complex that drives the movement of cargos along microtubules within cilia and flagella in concert with the intraflagellar transport (IFT) system, facilitating the assembly of these organelles. Involved in the regulation of ciliary length.
Synonyms: D2LIC; LIC3; CGI-60; DKFZP564A033
Tractability: Small molecule: a structure with a bound ligand is known. PROTAC: ubiquitination databases record sites on it; its protein half-life has been measured.
Gene: Protein-coding gene on chromosome 2 (43,774,039 to 43,810,012, forward strand). Ensembl gene ENSG00000138036.
Subcellular location: Golgi apparatus; Cytoplasm; Cell projection, cilium; Cytoplasm, cytoskeleton, cilium basal body; Cytoplasm, cytoskeleton, cilium axoneme; Cytoplasm, cytoskeleton, microtubule organizing center, centrosome
Subcellular location (Human Protein Atlas): Cytosol; Mid piece; Annulus; Basal body; Equatorial segment; Perinuclear theca; Primary cilium; Principal piece
Pathways (Reactome):
Organelle biogenesis and maintenance: Intraflagellar transport
Gene Ontology:
Molecular function: dynein heavy chain binding; protein binding
Biological process: intraciliary transport involved in cilium assembly; regulation of cilium assembly; intraciliary retrograde transport
Cellular component: centrosome; ciliary basal body; ciliary transition zone; cilium; cytoplasm; cytoplasmic dynein complex; cytosol; Golgi apparatus; apical part of cell; axoneme; ciliary tip; cytoplasmic microtubule; dynein complex; male germ cell nucleus; motile cilium
Genetic constraint (gnomAD): Loss-of-function variants: 10 observed, 16.5 expected, observed/expected ratio (o/e) 0.61, 90% interval 0.37 to 1.03. The upper end of that interval is the gene's LOEUF score, 1.03, which puts it in group 4 of 6, group 1 being the genes least tolerant of losing a copy. Missense variants: 196 observed, 165.85 expected, observed/expected ratio (o/e) 1.18, 90% interval 1.05 to 1.33. Synonymous variants: 49 observed, 55.37 expected, observed/expected ratio (o/e) 0.89, 90% interval 0.7 to 1.12.
Homologues: Orthologues: chimpanzee DYNC2LI1 (98% identical), pig DYNC2LI1 (92% identical), rabbit DYNC2LI1 (91% identical), dog DYNC2LI1 (91% identical), guinea pig DYNC2LI1 (89% identical), mouse Dync2li1 (88% identical), macaque DYNC2LI1 (86% identical), rat Dync2li1 (84% identical), tropical clawed frog dync2li1 (67% identical), zebrafish dync2li1 (60% identical), Caenorhabditis elegans xbx-1 (34% identical), Drosophila melanogaster CG3769 (32% identical).
Diseases named in the same sentence as DYNC2LI1 in open-access papers:
DYNC2LI1 is named in the same sentence as 6 diseases in open-access papers, as found by Europe PMC text mining. Sharing a sentence is not in itself a finding about the gene and the disease. The quoted sentences say what the papers report.
ciliopathies (7 papers, 2021 to 2025). "We constructed shRNAs to knock down Dync2li1, a ciliopathy gene encoding cytoplasmic dynein-2 light intermediate chain 1, and confirmed that Dync2li1 expression levels decreased in cells expressing Dync2li1-shRNA2, Dync2li1-shRNA3, Dync2li1-shRNA5, and Dync2li1-shRNA6." (PMID 39293864, 2024). "DYNC2LI1 functions in the dynein motor complex, crucial for retrograde transport in cilia, with implications for ciliopathies affecting development and organ function." (PMID 40624693, 2025). "Multiple ciliopathies caused by mutations in DYNC2H1, WDR60, WDR34, DYNC2LI1 and TCTEX1D2 have been reported." (PMID 36632779, 2023). "CFAP45 and PROM1 are found in both atypical and secondary ciliopathies, whereas TTC26, SCLT1, DNAJB11, DYNC2LI1, ALMS1, IFT80 and IFT74 are shared between primary and atypical ciliopathies." (PMID 37542408, 2023).
DYNC2LI1 also shares sentences with these, for which no sentence is quoted: short rib-polydactyly syndrome (2 papers); Ellis-van Creveld syndrome (1); genetic disease (1); Jeune syndrome (1); spondyloepimetaphyseal dysplasia (1).